ADORA2A (adenosine A2a receptor)
Diseases named in the same sentence as ADORA2A in open-access papers (continued):
Sharing a sentence is not in itself a finding about the gene and the disease.
Anxiety (continued). "Athletes who are more prone to performance anxiety may exacerbate their risk for feelings of anxiety depending on their caffeine use and which variant of the ADORA2A gene they possess." (PMID 33388079, 2021). "These adverse effects of caffeine may be particularly relevant in athletes that have a specific polymorphism of the adenosine A2A receptor (ADORA2A) gene that is associated with greater anxiety responses to caffeine ingestion." (PMID 31277403, 2019). "Finally, investigating a better understanding of the effects of caffeine on anxiety and sleep in sensitive subpopulations as well as in individuals with polymorphisms (e.g., ADORA2A) would be of use." (PMID 30340340, 2018). "Therefore, the upregulation of vGluT1 may underlie the effect of caffeine on anxiety via inhibition of vHPC adenosine A2A receptor." (PMID 35185566, 2022). "What is more, polymorphism c.1976T>C (rs5751876) in gene ADORA2A (adenosine A2A receptor) has been shown to modulate sleep-wake activity, contribute to individual sensitivity to caffeine’s effects on sleep, increasing susceptibility to caffeine-induced anxiety." (PMID 33668219, 2021). "Significant associations were also found between other ADORA2A and DRD2 receptor gene polymorphisms and post‐caffeine anxiety." (PMID 41549915, 2026). "Under chronic social defeat stress, resilient mice display downregulated Adora2a mRNA and reduced PSD-95 levels, consistent with attenuated excitatory drive, while susceptible mice maintain A2A receptor activity and show anxiety-like behaviors." (PMID 41535618, 2026). "As an example, genetic variations in the adenosine A2a receptor gene result in greater caffeine‐induced anxiety in light caffeine consumers." (PMID 41549915, 2026). "It has been reported that ADORA2A can regulate microglial remodeling in a mouse model of chronic anxiety, thereby reducing the anxiety-related behaviors in the mice." (PMID 35237278, 2022). "All the evidence suggests that the hippocampal adenosine A2A receptor is likely to emerge as an important receptor in the regulation of caffeine on memory and anxiety." (PMID 35185566, 2022). "The altered expression of four anxiety-related genes, c-Fos, Adora2a, BDNF, and AGRN were additionally confirmed by RT-qPCR." (PMID 35491423, 2022). "A common variation in the ADORA2A (adenosine A2A receptor) gene contributes to the differences in subjective feelings of anxiety after caffeine ingestion, especially in those who are habitually low caffeine consumers." (PMID 33388079, 2021). "The six ADORA2A SNPs, selected because of their involvement in caffeine consumption, sensitivity to caffeine effects on sleep, sleep disorders and anxiety in literature, were rs5751876, rs2298383, rs3761422, rs5751862, rs2236624, and rs4822492." (PMID 31817803, 2019). "Finally, combinations of ADORA2A and DRD2 polymorphisms have been reported, which account for more variation in caffeine‐induced anxiety compared to when they are isolated from each other." (PMID 41549915, 2026). "Research suggests that variants in the Adenosine Receptor A2a (ADORA2A) gene may influence an individual’s response to caffeine, leading to caffeine-induced anxiety and insomnia." (PMID 39648354, 2025). "For example, gene Adora2a (Adenosine A2a Receptor), an adenosine receptor group of G-protein-coupled receptors controlling synaptic plasticity, plays a critical role to modulate anxiety and sleep." (PMID 38827413, 2024). "This protein network insinuates a mechanism whereby Necab2—Adora2a interaction reduces Adora2a plasma membrane expression, creating an environment where more dopamine can bind to its receptor and potentially protect against anxiety-like behaviors." (PMID 37228107, 2023). "It is unclear whether caffeine regulates anxiety through the alteration of vGluT1, but the activation of adenosine A2A receptor has been reported to reduce GluT and glutamate uptake in cultured astrocytes and gliosomes." (PMID 35185566, 2022).
Anxiety (continued). "The Adora2a-knockout mice showed more anxiety than the wild-type mice did22,23." (PMID 33846458, 2021). "The 1976T>C polymorphism of ADORA2A modulates the EEG activity of the wake–sleep continuum, contributes to individual sensitivity to caffeine effects on sleep and greater sensitivity to caffeine-induced anxiety." (PMID 31817803, 2019). "As caffeine ergogenicity has been mostly associated with the blockage of the “fatiguing” action of adenosine on its receptors, and variations of ADORA2A have been suggested as an explanation for the individual sensitivity to caffeine effects on sleep, anxiety, and cognitive performance." (PMID 28287486, 2017). "Moreover, some studies have found that caffeine reverts memory impairment in a depression-prone mouse strain with upregulation of adenosine A2A receptors in the hippocampus, while selective A2AR knockout in the forebrain region (striatum, hippocampus, and cortex) induces anxiety-like behavior." (PMID 35185566, 2022). "Compounds such as acetylshikonin and 2-methyl-n-butyrylshikonin regulate neuroactive ligand-receptor interaction pathways through targets such as recombinant adenosine a1 receptor (ADORA1) and adenosine a2a receptor (ADORA2A), allowing exertion of anti-anxiety effects." (PMID 37169837, 2023). "An example for such non-linear effects on anxiety-phenotype is the Caffeinen-ADORA2A Genotype-Interaction." (PMID 34837533, 2022). "Many genes, such as ADORA2A, NPY, DRD2, GABRB3, has shown relation with panic disorder in few studies, with supporting evidence of each gene having relation with panic disorder or, in part, anxiety related function." (PMID 31435520, 2018). "Interestingly, one study demonstrated that self-reported anxiety with caffeine was not apparent in subjects possessing ADORA2A (rs5751876) TT who habitually consume large to moderate doses." (PMID 30257492, 2018). "Thus, we found that non-OCD anxiety disorders were related to variants of the two studied genes: rs2228079 of ADORA1 (not reaching significance) and rs5751876 of ADORA2A (significantly), which is not in line with earlier reports considering anxiety symptoms as secondary to GTS." (PMID 26317759, 2015). "All CaffEQ-BR factors, for the full and brief versions, were ICCs > 0.75, except for factor 6 (anxiety/negative effects; ICC = 0.60), and presented ROC curve values from 0.464 to 0.624 and 0.443 to 0.575 for CYP1A2 and ADORA2A." (PMID 36014860, 2022).
melanoma (43 papers, 2015 to 2026). A malignant, usually aggressive tumor composed of atypical, neoplastic melanocytes. "combined adenosine A2A receptor (A2AR) antagonist with BRAF and MEK inhibition in melanoma cell lines and murine melanoma BRAF-mutated models." (PMID 36131912, 2022). "Our results showed that THOC2 inhibition significantly reduced the expression of PDE4D, PIK3CA, GNAI1, ADCY1, HHIP and ADORA2A in melanoma cells." (PMID 31680623, 2019). "The ADORA2a and A2b were differentially expressed by the subsets whose proliferation is less inhibited by melanoma cell lines (i.e. naïve CD4+ T cells and effector CD8+ T cells) when compared to other cell subsets." (PMID 26329660, 2015). "To assess if the same pattern of expression was conserved in the TME, we analyzed a public dataset of scRNAseq from melanoma tissues, and we confirmed that tumor-infiltrating B cells almost exclusively expressed ADORA2A, at highest levels in GC B cell-like and PC-like cells." (PMID 41472728, 2025). "In particular, the adenosine A2A receptor (ADORA2a) has been found to be overexpressed in HNSCC and in several melanoma and breast cancer cell lines." (PMID 33467713, 2021). "In addition, adenosine A2a receptor (ADORA2A) antagonists synergize with a variety of immunotherapeutic strategies in a variety of preclinical tumor models, including CAR T-cell therapies in a leukemia model and PD-1 blockers in breast cancer and melanoma models." (PMID 40356913, 2025).
Alzheimer disease (41 papers, 2012 to 2025). A progressive, neurodegenerative disease characterized by loss of function and death of nerve cells in several areas of the brain leading to loss of cognitive function such as memory and language. "Studies have shown that ADORA2A is highly expressed in Alzheimer’s disease, and ADORA2A is an independent risk factor for Alzheimer’s disease." (PMID 37945707, 2023). "There is a genetic association of the adenosine A2A receptor encoding gene (ADORA2A) with hippocampal volume in mild cognitive impairment and Alzheimer’s disease." (PMID 29950682, 2020). "SLC35A4 is related to epileptic encephalopathy, while H19, ADORA2A and INPP5D are linked to cognitive impairment and Alzheimer's disease." (PMID 39020437, 2024). "Caffeine may also confer neuroprotection in Alzheimer’s disease by mitigating β-amyloid-induced neuronal damage through adenosine A2A receptor inhibition." (PMID 41350392, 2025). "Caffeine is associated with procognitive effects in humans by counteracting overactivation of the adenosine A2A receptor (A2AR), which is upregulated in the human forebrain of aged and Alzheimer’s disease (AD) patients." (PMID 27510168, 2016). "Consumption of caffeine, a non-selective adenosine A2A receptor (A2AR) antagonist, reduces the risk of developing Alzheimer’s disease (AD) and mitigates both amyloid and Tau lesions in transgenic mouse models of the disease." (PMID 30050407, 2018). "The intracerebroventricular (icv) injection of amyloid peptides (Aβ) models Alzheimer’s disease (AD) in mice, as typified by the onset within 15 days of deficits of memory and of hippocampal long-term potentiation (LTP) that are prevented by the blockade of adenosine A2A receptors (A2AR)." (PMID 37627238, 2023).
Cognitive impairment (31 papers, 2014 to 2025). Abnormal cognition is characterized by deficits in thinking, reasoning, or remembering. "The over-activation of adenosine A2A receptors (A2AR) is closely implicated in cognitive impairments of Alzheimer's disease (AD)." (PMID 37899431, 2023). "A gene-based association analysis identified ADORA2A associated with hippocampal volume in mild cognitive impairment and AD40." (PMID 33154420, 2020). "In line with a role of A2ARs in AD, an association between a polymorphism of the ADORA2A gene with hippocampal volume in mild cognitive impairment and AD has been recently reported." (PMID 30050407, 2018). "Additionally, a polymorphism of the adenosine A2a receptor (ADORA2A) gene has been reported to be associated with hippocampal volume in mild cognitive impairment and AD patients." (PMID 31781354, 2019). "Recently, an association between a polymorphism of the adenosine A2A receptor (A2AR) encoding gene—ADORA2A, with hippocampal volume (synaptic loss) in mild cognitive impairment and AD was reported." (PMID 29950682, 2020). "On the other hand, the group of Bergamaschini detected different levels of ADORA2A mRNA and its cognate receptor in patients with diverse grade of cognitive impairment." (PMID 28529533, 2017). "Finally, recently it has been demonstrated that, in addition to the negative allosteric effect on the CB1 receptor, CBD affects the Δ9-THC cognitive impairment in an adenosine A2A receptor (A2AR)-dependent manner." (PMID 32357565, 2020). "Moreover, both caffeine and adenosine A2a receptor antagonists prevent Aβ-induced cognitive deficits in mice." (PMID 24828424, 2014). "Our statistical analysis on mental damage in both centenarian subgroups indicates, that their grade of cognitive impairment, is independent of ADORA2A mRNA levels." (PMID 28529533, 2017). "Additionally, adenosine A2A receptor mRNA level of centenarians, did not correlate with their cognitive impairment." (PMID 28529533, 2017).
depression (29 papers, 2006 to 2025). "Stress-induced up-regulation of ADORA2A can lead to alterations in neuronal function, promoting depression-like symptoms." (PMID 40243466, 2025). "Istradefylline as an adenosine A2A receptor antagonist improved daytime sleepiness, apathy, depression, and lower urinary tract symptoms in PD patients." (PMID 35193486, 2023). "In 2001, Berk showed that the function of the adenosine A2a receptor was weakened in platelets of patients with depression." (PMID 31334608, 2019). "Taken together, these results consolidated that the dynamic link between RagA and ADORA2A might play a role in depression although little is known about the mechanism by which RagA overexpression induces ADORA2A." (PMID 39373701, 2024). "Therefore, ADORA2A up-regulation may serve as both a biomarker and a therapeutic target for depression." (PMID 40243466, 2025).
schizophrenia (28 papers, 2009 to 2025). A major psychotic disorder characterized by abnormalities in the perception or expression of reality. "Recent research has suggested an association between schizophrenia risk and genetic variation at a single nucleotide polymorphism (SNP) within the adenosine A2R (ADORA2A) gene." (PMID 38758511, 2025). "On chromosome 22q12–13, a single nucleotide polymorphism (SNP) on the A2a receptor provides a candidate schizophrenia susceptibility gene, which, again, ties the adenosine A2a receptor to various mental disorders that include schizophrenia, as well as depression and anxiety." (PMID 36187336, 2022). "In the same covariate analyses, when considering trend-significant associations, we identified genes such as TRIM10 and GAS7, associated with schizophrenia, MACROH2A1, related to autism-like behaviors, and ADORA2A, associated with anxiety disorders." (PMID 39020437, 2024). "Reports of elevated ADORA2A expression in the hippocampus and striatum of patients with schizophrenia have been interpreted as a compensatory upregulation in response to reduced adenosine availability." (PMID 36998267, 2023). "Second, there has been suggestions that reduction in A2A receptor levels are only present in a subgroup of schizophrenia patients, particularly in those with DNA methylation of the gene coding for A2AR (ADORA2A)." (PMID 34175983, 2022). "In murine models of schizophrenia, GDNF was shown to activate adenosine A2a receptor (A2AR), a G protein-coupled receptor that modulates dopaminergic signaling and could be a trigger for hyperdopaminergia." (PMID 41562905, 2025).
Dyskinesia (27 papers, 2012 to 2025). A movement disorder which consists of effects including diminished voluntary movements and the presence of involuntary movements. "Adenosine A2A receptor antagonists may reduce the severity of dyskinesia, which is associated with greater receptor availability in PD patients who develop LID." (PMID 34640395, 2021). "Variants in ADORA2A SNPs and HOMER1 have been linked to L-dopa -induced dyskinesia and psychotic symptoms." (PMID 39392484, 2025). "In turn, an increase in ADORA2A expression can lead to the development of dyskinesia in treated PD patients." (PMID 38027039, 2023). "The studies focused on developing an adenosine A2A receptor (A2AR) tracer, with antagonists of A2AR, to evaluate the A2AR upregulation observed in the striatum of PD, which appears to be related to dyskinesia." (PMID 36797611, 2023). "In American (AMR) population, Brazilians constituted four studies determining rs4704559 (HOMER1), rs2298383 (ADORA2A), rs1800497 (ANKK1) associated with dyskinesia, rs3761422 (ADORA2A) with motor fluctuation and rs28363170 (DAT1) with hallucination." (PMID 28927418, 2017). "While these compounds are currently in different testing phases, a few studies using adenosine A2A receptor antagonists and mGluR5 antagonists have demonstrated a significant reduction in dyskinesia induction in animal models and subgroups of human samples." (PMID 23514355, 2013). "Future avenues for drug treatment of dyskinesia include the development of adenosine A2A receptor antagonists as well as the use of metabotropic glutamate receptor 5 (mGluR5) antagonists and orthosteric metabotropic glutamate receptor 4 (mGluR4) agonists." (PMID 23514355, 2013). "Istradefylline, an FDA-approved adenosine A2A receptor antagonist currently used for treating PD, reduces off time and improves the motor symptoms of patients with PD albeit with complications including the exacerbation of dyskinesia." (PMID 32580456, 2020). "In a study, it was observed that MPTP-treated monkeys with dyskinesia have an upregulated expression of adenosine A2A receptor, compared with non-dyskinetic MPTP treated monkeys." (PMID 35462934, 2022). "Preladenant, an adenosine A2A receptor antagonist, was observed to be improving the on time associated with L-DOPA therapy, without changing the dyskinesia state in individuals with moderate to severe PD in a double-blinded, placebo-controlled RCT." (PMID 35462934, 2022). "Istradefylline (Adenosine A2A Receptor antagonist) effectively alleviates motor impairments in combination with low dose dopaminergic drug without aggravating dyskinesia." (PMID 26988916, 2016).
ischemia (24 papers, 2011 to 2025). A hypoperfusion of the BLOOD through an organ or tissue caused by a PATHOLOGIC CONSTRICTION or obstruction of its BLOOD VESSELS, or an absence of BLOOD CIRCULATION. "The myocardial protection of adenosine A2a receptor after ischemia may involve the cAMP-PKA signaling pathway and the interaction of Bcl-2-Beclin-1." (PMID 35571159, 2022). "In particular, the adenosine A2A receptor (A2AR) is a class A GPCR that is important for treatment of sickle cell disease, cancer, inflammation, ischemia, neuronal disorders and various infectious diseases." (PMID 33723285, 2021). "Studies in healthy animals have shown that the activation of AdorA2a prior to ischemia does not result in a reduction of myocardial I/R injury." (PMID 27757725, 2016). "The binding between ACE2 and ADORA2A points to a possible mechanism where ACE2 modulates adenosine-mediated vasodilation, which could have protective effects on the cardiovascular system under conditions of stress or ischemia." (PMID 40142959, 2025). "Therefore, we determined the effect of CLP on AdorA2a and AdorA2b mRNA expression in the right and left ventricle with or without ischemia." (PMID 27757725, 2016).
memory impairment (22 papers, 2012 to 2024). "This research explores caffeine's modulation of the adenosine A2A receptor (A2AR) and its regulatory effects on tyrosine hydroxylase (TH), aiming to restore dopamine homeostasis and mitigate memory impairments associated with hypoxia." (PMID 39670604, 2024). "In this context functional studies showed the protective role of coffee consumption against AD and T2D-associated memory impairment through adenosine A2 receptor (ADORA2A) blockage." (PMID 37342358, 2023). "Further, there is strong evidence that Adora2A is a regulator of synaptic plasticity and, interestingly, the upregulation of this transcript in ageing and in AD is associated with memory impairment." (PMID 34502030, 2021). "Studies have shown that caffeine's effects on memory impairment resemble those of selective adenosine A2A receptor (A2AR) antagonists, implicating the A2AR in caffeine's cognitive benefits." (PMID 39670604, 2024).